INS (insulin)
Diseases named in the same sentence as INS in open-access papers (continued):
Sharing a sentence is not in itself a finding about the gene and the disease.
Insulin resistance (continued). "A main group effect was observed for homeostatic model assessment of insulin resistance (P = 0·036, F = 3·79) and composite insulin sensitivity index score (P = 0·026, F = 4·23)." (PMID 39927497, 2025). "In diabetic patients, impaired insulin secretion or insulin resistance disrupts metabolism and cell signal transduction." (PMID 41208872, 2025). "This systemic inflammation can interfere with insulin signaling, contributing to insulin resistance and poor glycemic control." (PMID 40418274, 2025). "The homeostasis model HOMA-IR, β-cell function (%B), and insulin sensitivity (%S) are computational frameworks designed to quantify insulin resistance, functioning of pancreatic β-cell, and insulin sensitivity index in pre-clinical and clinical studies." (PMID 41227734, 2025). "In turn, oxidative stress and inflammation further aggravate insulin resistance and impair insulin secretion, establishing a self-reinforcing cycle." (PMID 41156447, 2025). "A recent meta-analysis demonstrated that zinc supplementation significantly reduced fasting blood glucose, glycosylated hemoglobin (HbA1c), serum insulin, and insulin resistance as estimated by the homeostasis model assessment (HOMA-IR)." (PMID 40647294, 2025). "Vitamin D reduces inflammation, regulates Ca2+ homeostasis, and reduces insulin resistance, which improves glucose and lipid metabolism in insulin-sensitive tissues." (PMID 41211221, 2025). "The most frequently reported metabolic markers were fasting plasma glucose (FPG), fasting insulin, Homoeostatic Model Assessment of Insulin Resistance (HOMA-IR), haemoglobin A1c (HbA1c), and adiponectin (APN)." (PMID 39487296, 2025). "Overall, the study demonstrated that 8 weeks of HIIT can improve insulin signaling and enhance skeletal muscle oxidative capacity in individuals with obesity, particularly benefiting those with baseline insulin resistance." (PMID 40867832, 2025). "This study suggests that nidulin partially mimics insulin action holding potential as a novel insulin-sensitizing agent, highlight the potential of nidulin as an adjunctive therapy for insulin resistance and T2D." (PMID 40932616, 2025). "Infant adiposity significantly correlated with insulin resistance r = 0.731, P < 0.01) and fasting insulin (r = 0.697, P = 0.01) among GDM mothers at 37th gestational week." (PMID 40078500, 2025). "The notable occurrence of insulin resistance with euglycemic profiles demonstrated in our study signals potential alterations in insulin action in individuals with chronic SCI." (PMID 40363903, 2025). "In vivo and in vitro rodent models showed that acrylamide leads to insulin resistance and increased blood sugar through oxidative stress on beta cells, disrupting glucose metabolism and insulin signaling pathways." (PMID 40255553, 2025). "Among them, isoleucine is known for its protective role against insulin resistance by stimulating insulin‐independent glucose uptake in skeletal muscle cells." (PMID 39810724, 2025). "In early stages of T2D pathogenesis, the body produces insulin, but its ability to reduce blood glucose levels is inadequate (insulin resistance)." (PMID 38895272, 2025). "Insulin resistance and decreased insulin or IGF-1 levels affect Akt phosphorylation and phosphorylated GSK3β levels, which promote the breakdown of β-catenin." (PMID 40725728, 2025). "Specifically, caffeinated coffee increased circulating adiponectin, a hormone that enhances insulin sensitivity, whereas decaffeinated coffee significantly reduced the levels of fetuin-A, a hepatokine as-sociated with insulin resistance." (PMID 40565007, 2025). "In T2DM, cells develop insulin resistance, or the pancreas produces insufficient insulin, leading to inefficient glucose uptake and elevated blood sugar levels." (PMID 40742490, 2025). "The results for fasting blood glucose (FBG), plasma insulin, insulin resistance (HOMA-IR), and glycated hemoglobin (HbA1C) were consistent with the results of the OGTT assessment." (PMID 40563879, 2025).
Insulin resistance (continued). "Oxidative stress is a major contributor to the pathophysiology of T2DM, leading to β-cell dysfunction, impaired insulin signaling, mitochondrial alterations, and insulin resistance." (PMID 41441014, 2025). "This underscores that monitoring must be coupled with targeted interventions—such as intranasal insulin, which acts on specific pathways like neuroinflammation and insulin resistance—to meaningfully improve outcomes." (PMID 41312480, 2025). "Chronic high acid intake can induce low-grade metabolic acidosis, which has been shown to impair insulin signaling and promote insulin resistance—a fundamental driver of adipogenesis and obesity." (PMID 41305607, 2025). "The adipose tissue insulin resistance (Adipo-IR) index was calculated using plasma insulin and free fatty acid levels, both of which were found to be significantly higher in DP mice compared to DR." (PMID 41361331, 2025). "Experimental studies indicate that JLD acts on multiple biological targets, enhancing pancreatic β-cell function, stimulating insulin secretion, preventing β-cell apoptosis, and improving insulin resistance." (PMID 41334442, 2025). "Because inflammatory cytokines from visceral fat disrupt insulin signaling, inflammation plays a role in insulin resistance." (PMID 39940428, 2025). "Mechanistically, JAK2 overexpression amplifies the insulin promoter activity, whereas phosphorylated STAT3 impairs the insulin signaling and glucose uptake in skeletal muscle, driving insulin resistance." (PMID 40831950, 2025). "This inflammatory response is marked by elevated levels of cytokines such as IL-6, tumor necrosis factor-aplha (TNF-α), and C-reactive protein, which can impair insulin signaling pathways and contribute to insulin resistance." (PMID 40964166, 2025). "In individuals with insulin resistance, however, cellular responsiveness to insulin is impaired, hindering glucose uptake and leading to elevated blood sugar levels." (PMID 40687580, 2025). "This decrease in insulin levels indicates an improvement in insulin sensitivity, which is crucial for managing T2 DM and insulin resistance." (PMID 40565030, 2025). "Insulin resistance (IR) is a health disorder in which tissues exhibit a reduced response to the circulating glucose uptake stimulated by insulin." (PMID 40289929, 2025). "Obesity, impacting 40–85% of women with PCOS, exacerbates insulin resistance, increases insulin levels, and intensifies low-grade inflammation." (PMID 41010046, 2025). "Stress-induced hyperglycemia is characterized by decreased insulin secretion and increased insulin resistance, further complicating glucose metabolism." (PMID 41349476, 2025). "Restores insulin sensitivity, enhances glucose uptake, reverses palmitate-induced insulin resistance, reduces IRS-1 serine phosphorylation, activates AMPK, improves GLUT4 translocation." (PMID 39963239, 2025). "Insulin-resistant human monocytes displayed lower IR tyrosine kinase activity, and the monocyte/macrophage insulin resistance theory is gaining momentum." (PMID 40141412, 2025). "This is supported by studies linking inflammatory biomarkers, such as high-sensitivity C-reactive protein, to changes in insulin dynamics, which exacerbate insulin resistance and contribute to the pathology of diabetes." (PMID 40002771, 2025). "Meanwhile, Sult2b1KO mice also showed significantly lower fasting blood insulin levels and insulin resistance index homeostatic model assessment-insulin resistance (HOMA-IR)." (PMID 40456448, 2025). "Ectopic accumulation of circulating fatty acids in insulin-responsive tissues can further exacerbate insulin resistance, reducing the normal insulin response." (PMID 41227271, 2025). "Conversely, reduced HDL-C levels lead to excessive cholesterol buildup in insulin-sensitive tissues, triggering insulin resistance through inflammation and macrophage infiltration." (PMID 40475963, 2025).
Insulin resistance (continued). "It was observed that Nrf2 activation for a shorter time period results in improved insulin resistance status, while uninterrupted activation leads to impaired insulin signaling due to the excessive removal of reactive oxygen species." (PMID 40728998, 2025). "Conversely, an alternate framework describes hyperinsulinemia as a primary defect and insulin resistance as a protective response of tissues against insulin-induced nutrient overload and metabolic stress." (PMID 40013621, 2025). "Insulin resistance is a condition in which cells become less responsive to the effects of insulin, leading to impaired glucose uptake and utilization." (PMID 40290665, 2025). "Insulin resistance (IR) is a pathological condition in which the body’s cells become less responsive to the action of insulin, leading to elevated blood insulin levels." (PMID 41002547, 2025). "A protective effect against gestational diabetes is also debated, as DUSP9 affects insulin resistance and generally has a complex role in insulin signaling, glucose uptake, and related metabolic processes." (PMID 40564984, 2025). "For many years, the prevailing view was that insulin resistance (that is, resistance to insulin’s role in promoting glucose uptake by muscle and fat cells) preceded and caused hyperinsulinemia." (PMID 41009753, 2025). "Insulin resistance (IR) refers to the reduced sensitivity or responsiveness of target organs such as the liver, skeletal muscles, or adipose tissue to insulin." (PMID 40512995, 2025). "Given that GDM-I patients require insulin therapy due to more pronounced insulin resistance, it is likely that both endogenous insulin resistance and exogenous insulin treatment contribute to PKM2 activation." (PMID 40136665, 2025). "Insulin resistance (IR) reduces the sensitivity of muscle and fatty tissues to insulin and diminishes the sensitivity of the liver to suppress hepatic glucose production and output." (PMID 40093882, 2025). "Insulin resistance (IR) manifests through diminished insulin efficacy in facilitating glucose absorption and utilization within peripheral tissues, resulting in a compensatory increase in insulin levels." (PMID 41291174, 2025). "The first observed abnormality of insulin resistance is the insulin-induced decrease in glucose uptake in AT and skeletal muscle." (PMID 40076851, 2025). "Insulin resistance markers, including fasting insulin and HOMA-IR, contributed primarily to the second dimension." (PMID 41422312, 2025). "Increased abdominal fat leads to the release of free fatty acids, which interfere with insulin signaling and trigger systemic insulin resistance." (PMID 41488045, 2025). "Specifically, it has been shown that the activation of NOD1 reduces insulin-induced glucose uptake, indicating a direct link between innate immunity and insulin resistance in human adipocytes." (PMID 41226484, 2025). "Initially, the pancreas compensates for insulin resistance by increasing insulin production; however, over time, this compensatory mechanism fails, leading to sustained hyperglycemia, which is a hallmark of type 2 diabetes." (PMID 40687580, 2025). "In participants with type 1 diabetes, muscle insulin resistance additionally correlated directly with HbA1c, insulin dose, mean overnight glucose, and inversely with glycemic variability." (PMID 41285865, 2025). "DM manifests primarily as Type 1 DM, characterized by inadequate insulin production, and Type 2 DM, characterized by insulin resistance or insufficient insulin secretion, accounting for over 90% of cases." (PMID 40575395, 2025). "The state in which the mechanisms of responsiveness to physiological levels of insulin are impaired is described as insulin resistance." (PMID 41009549, 2025). "While primary hepatocyte-specific ChREBP overexpression improved insulin sensitivity, a high-fat diet–fed mice model, which also shows increased ChREBP levels, showed insulin resistance." (PMID 40311678, 2025).
Insulin resistance (continued). "It inhibits insulin signaling via glucose and fatty acid metabolism regulation, promoting the development of insulin resistance (IR), and is involved in proangiogenic and proinflammatory protein expression modulation." (PMID 40943138, 2025). "Insulin resistance is a metabolic condition in which peripheral tissues, such as muscle, liver, and adipose tissue, exhibit a reduced response to insulin’s effects, leading to pancreatic compensation through increased insulin secretion (hyperinsulinemia)." (PMID 40943494, 2025). "TNFα induces insulin resistance by directly inhibiting the insulin signaling pathway, modulating mitochondrial oxidative phosphorylation (OxPhos), and inducing oxidative stress signaling pathways." (PMID 39269560, 2025). "Macrophages have functional insulin signaling, and they develop insulin resistance in the context of systemic insulin resistance." (PMID 39198360, 2025). "A study showing that liver fat concentration influences insulin sensitivity in people far more than visceral fat mass does suggests that fatty liver plays a direct and significant role in the pathophysiology of insulin resistance." (PMID 39997251, 2025). "The triglyceride-glucose (TyG) index is a recognized marker for estimating insulin levels and is considered more reliable than the homeostasis model assessment of insulin resistance in healthy individuals." (PMID 41019331, 2025). "Although the risk of insulin resistance is known to increase with age, in the current study, a negative correlation was rather observed between age and HOMA-IR, WHR, HDL and insulin but positive with galectin-3 in respondents with T2DM without malaria." (PMID 40802820, 2025). "The study’s findings showed that propolis ingestion, along with exercise, significantly lowered insulin, insulin resistance (IR), fasting blood glucose (FBG), and glycosylated hemoglobin at the same time." (PMID 40078415, 2025). "The vitamin combination had the best beneficial effect on lipid metabolism and the vascular system through the most reducing effect on IL-1β, NF-kβ signaling, insulin, insulin resistance, FFAs, MGO, and AGEs." (PMID 39877627, 2025). "Insulin resistance (IR), defined as a defect in insulin-mediated control of glucose metabolism in key organs such as the muscle, fat, and liver, is 1 of the earliest metabolic comorbidities of obesity." (PMID 40862085, 2025). "It plays a crucial role in metabolic adjustments, particularly in conditions like obesity and insulin resistance, and is vital for maintaining the body's balance, accounting for over 75% of insulin‐mediated glucose disposal." (PMID 40522107, 2025). "T2D is characterised by a complex metabolic dysfunction, primarily involving insulin resistance and a relative deficit in insulin secretion." (PMID 40892247, 2025). "Abdominal fat accumulation increases insulin resistance, and lipotoxicity with dysregulated adipokine secretion enhances insulin sensitivity." (PMID 40084339, 2025). "To assess basal insulin levels as an indicator of metabolic status and possible insulin resistance, we additionally collected fasted blood from the periorbital vein plexus at 14 and 24 weeks of age and measured plasma insulin concentration." (PMID 41199860, 2025). "In conclusion, circulating miRNAs play a crucial role in the regulation of insulin signaling and glucose metabolism, making them key contributors to the development and progression of insulin resistance." (PMID 40565979, 2025). "Excessive high-fat diet interferes with the insulin signaling pathway in adipose tissues, which leads to insulin resistance." (PMID 41002956, 2025). "In our study, most subjects maintained appropriate salivary values; however, it is well-established that individuals with obesity often exhibit elevated insulin levels, further contributing to insulin resistance." (PMID 40531756, 2025).
Insulin resistance (continued). "Metformin, recognized as an insulin sensitizer, has demonstrated efficacy in enhancing endothelial function, with a notable correlation between endothelial function and insulin resistance following treatment in individuals diagnosed with T2DM." (PMID 40093018, 2025). "At the age of 4 years, laboratory tests revealed slightly elevated fasting insulin levels, indicative of insulin resistance, but normal HbA1c and fasting glucose levels." (PMID 40842493, 2025). "This pro-inflammatory and oxidative environment disrupts insulin signaling and fosters ectopic lipid accumulation in the liver and the skeletal muscle, further aggravating insulin resistance." (PMID 40563357, 2025). "Non-insulin medicines licensed for treating T2DM have various modes of action, including stimulating insulin secretion, altering gastrointestinal absorption, altering renal reabsorption of glucose, and reducing insulin resistance." (PMID 40651878, 2025). "Considering previous research showed that elevated levels of free fatty acids lead to insulin resistance, these findings provide more context for the observed hyperglycemia in KO rats but equivalent insulin responses to wild-type rats." (PMID 41385510, 2025). "In PCOS with Hashimoto’s thyroiditis (PCOS+HT), insulin resistance also correlates with fasting insulin, HOMA index, BMI, SHBG, and left ovarian volume." (PMID 40161019, 2025). "Glucose clamp studies of patients with insulinomas demonstrated that insulin resistance can develop in response to elevated insulin." (PMID 40013621, 2025). "Dysregulation of insulin results in health complications such as insulin resistance and hyperglycemia." (PMID 39786569, 2025). "The aim was to investigate the effects of rosuvastatin on intestinal microorganisms and metabolites in insulin-resistant mice, as well as to explore the relationship between rosuvastatin and the improvement of insulin resistance." (PMID 40661966, 2025). "Insulin resistance, which is the basic defect in T2D, will inherently dampen the muscle’s response to insulin signaling." (PMID 40870444, 2025). "Insulin resistance, characteristic of type 2 diabetes and a potential consequence of prolonged hyperglycemia, can disrupt brain insulin signaling, compromising neuronal function and cognition." (PMID 39822993, 2025). "Its use also decreased waist circumference, body fat percent, fasting blood glucose (FBG), insulin, homeostasis assessment model for insulin resistance (HOMA-IR), as well as MDA compared to the control group." (PMID 40343290, 2025). "Hepatic insulin resistance in MASLD has characteristics of mixed insulin resistance: preserved insulin-dependent lipogenic signaling and impaired insulin-dependent suppression of HGP." (PMID 41196673, 2025). "In a study of 80 women with PCOS, daily administration of 1,500 mg cinnamon powder capsules for 12 weeks significantly reduced fasting insulin and insulin resistance." (PMID 41141268, 2025). "In high-fat diet (HFD)-induced obese C57BL/6 mice, SW attenuated HFD-induced weight gain, glucose intolerance, and obesity-related insulin resistance by enhancing insulin signaling." (PMID 40801607, 2025). "TNF-α is a pro-inflammatory cytokine that impairs insulin signaling and intensifies insulin resistance." (PMID 40182806, 2025). "In the context of insulin resistance, the physiological roles of insulin in facilitating lipogenesis and inhibiting lipolysis are compromised." (PMID 40376582, 2025). "Elevated acetate production from high-calorie diets can lead to increased levels of hormones like ghrelin and insulin, promoting hyperphagia and storage of fat, leading to obesity, hyperlipidemia, and insulin resistance." (PMID 40535952, 2025). "Insulin resistance is characterized by the inability of various tissues to respond to normal circulating insulin levels adequately." (PMID 40076851, 2025).